OTUD6B-AS1 (OTUD6B antisense RNA 1)
Synonyms: GS1-251I9.4
Gene: Long non-coding RNA gene on chromosome 8 (91,059,318 to 91,070,583, reverse strand). Ensembl gene ENSG00000253738.
Diseases named in the same sentence as OTUD6B-AS1 in open-access papers:
OTUD6B-AS1 is named in the same sentence as 4 diseases in open-access papers, as found by Europe PMC text mining. Sharing a sentence is not in itself a finding about the gene and the disease. The quoted sentences say what the papers report.
clear cell renal cell carcinoma (1 paper, 2020). "lncRNA OTUD6B antisense RNA 1 (OTUD6B-AS1) is a tumor-suppressive noncoding RNA in clear cell renal cell carcinoma." (PMID 32256450, 2020).
triple-negative breast carcinoma (1 paper, 2024). An invasive breast carcinoma which is negative for expression of estrogen receptor (ER), progesterone receptor (PR), and human epidermal growth factor receptor 2 (HER2). "In addition, in triple-negative breast cancer, OTUD6B can activate autophagy and DDR inhibition through the OTUD6BAS1/miR-26a-5p/MTDH axis, thereby mediating genomic instability and promoting the development of PTX drug resistance." (PMID 38880876, 2024).
OTUD6B-AS1 also shares sentences with these, for which no sentence is quoted: breast carcinoma (1 paper); tumor (1).